BRAF (B-Raf proto-oncogene, serine/threonine kinase)
Diseases named in the same sentence as BRAF in open-access papers (continued):
Sharing a sentence is not in itself a finding about the gene and the disease.
rectal cancer (continued). "BRAF exon 15 codon 600 600Glu mutation was detected in 1 out of 140 (0.7%) rectal cancer samples." (PMID 30416987, 2018). "Additionally, more than half of the microRNAs with multimodal tumor-normal expression differences in rectal cancer have their significance associated with MSI (186 of 276) or BRAF tumor status (176 of 276)." (PMID 29084506, 2017). "However, among the limited number of BRAF mutation studies in Chinese patients, only one study performed a survival analysis in a sample of 314 patients, including colon and rectum cancers." (PMID 25367198, 2014). "Rectal cancers have higher rates of locoregional relapse, a preference for lung metastases and a lower frequency of KRAS and BRAF mutations." (PMID 39827162, 2025). "Among patients receiving systemic therapy only, mOS varied from 6 months in patients with BRAF-V600Emt left colon and rectal cancers to 23 months in patients with RAS&BRAFwt rectal cancers." (PMID 40437037, 2025). "The likeliest explanation for this discordant result is the fact that samples of locally advanced rectal cancer (LARC) patients were used, and a low percentage of BRAF mutations are expected." (PMID 33669856, 2021). "Mutations and CNA varied according to primary tumour site with BRAF mutations mainly seen in colon (49%), and FBXW7 mutations mainly seen in rectal cancers (25%)." (PMID 34647903, 2021). "Because only two BRAF V600E-mutant patients with rectal cancer were included, the result still needs to be confirmed in the future." (PMID 29666387, 2018). "In advanced stage CRCs, rectal cancers showed a higher frequency of KRAS mutation (p = 0.03); meanwhile, BRAF mutation was related to female sex (p = 0.04) and less lymph node invasion (p = 0.05)." (PMID 25734426, 2015). "Point mutations in KRAS, BRAF, and PIK3CA and ERBB2 amplification were determined in primary tumors from 63 patients with locally advanced rectal cancer scheduled for radical treatment." (PMID 23226389, 2012). "Frequencies of tumor KRAS, BRAF, and PIK3CA point mutations and ERBB2 amplification in 63 patients with locally advanced rectal cancer." (PMID 23226389, 2012). "Additionally, the rectal cancer exhibited proficient DNA mismatch repair (pMMR) status, ERBB2 copy number amplification, and a missense mutation, while the KRAS, NRAS, and BRAF genes were wild-type." (PMID 39985003, 2025). "The most common biomarker-associated therapy recommendation (nine cases) was the use of anti-EGFR therapy for patients with left-sided colon or rectal cancer in the absence of a contraindicating RAS/BRAF mutation." (PMID 39590164, 2024). "Finally, the performance of the circMET-based detection strategy was retrospectively assessed in a metastatic BRAF V600E-positive rectal cancer case." (PMID 37170152, 2023). "BRAF, FBXW7, PTEN, and SMAD4 mutations were observed in 20.7% of patients with rectal carcinoma." (PMID 36142267, 2022). "KRAS/NRAS/BRAF mutations were not significantly related to patients' age analyzed by Student's t-test in rectal cancer." (PMID 30416987, 2018). "Gaedcke and al detected no V600E BRAF mutations in 94 rectal cancer patients suggesting that BRAF mutations and consequently MLH1 gene promoter hypermethylation do not seem to play any role in rectal cancer pathogenesis." (PMID 26104511, 2015). "In this study, we aimed to determine the mutation frequencies of KRAS, BRAF and PIK3CA and to establish whether such mutations may be used as prognostic and/or predictive factors in rectal cancer patients." (PMID 23617638, 2013).
rectal cancer (continued). "Interestingly, both BRAF (P=0.000) and PIK3CA (P=0.011) mutations were significantly more frequent in colon than in sigmoid or rectal carcinomas." (PMID 23548132, 2013). "No mutations were detected in BRAF exon 15 in rectal carcinomas of the test series, but one (4%) MSI-H sigmoid carcinoma with no KRAS mutation presented the mutation c.1799T > A (V600E)." (PMID 20979647, 2010). "Therefore, efficient identification of RAS and BRAF status in rectal cancers using a non-invasive method, which could feasibly reveal the whole tumor gene features in real-time, would be of meaningful assistance in providing individual tailored therapy." (PMID 34395262, 2021). "High phosphatidylinositol-3-kinase-mediated signaling activity of the primary tumor, rather than KRAS/BRAF mutation status, was identified as a hallmark of poor metastasis-free survival in patients with locally advanced rectal cancer undergoing radical treatment of the pelvic cavity." (PMID 23226389, 2012). "In the RAS/BRAF‐wt subset, 1.3% were MSI‐H and 4.1% TMB‐H, whereas in the RAS/BRAF‐altered subset 2.0% were MSI‐H and 5.0% TMB‐H in rectal cancer (P < 0.05, Fisher's exact test)." (PMID 39865537, 2025). "In the subgroups receiving systemic therapy only, the shortest mOS was seen among BRAF-V600Emt/pMMR rectal cancers (6 months) and the longest among RAS&BRAFwt/pMMR rectal cancers (23 months)." (PMID 40437037, 2025). "In this study, we segmented rectal cancer via 3D V-Net on T2WI and DWI and then compared the radiomics performance in predicting KRAS/NRAS/BRAF status between DL-based auto segmentation and manual-based segmentation." (PMID 34395262, 2021). "In this study, 3D V-Net architecture provided reliable rectal cancer segmentation on T2WI and DWI compared with expert-based segmentation, and auto segmentation was subjected to radiomics analysis in the prediction of KRAS/NRAS/BRAF mutation status and may produce a good prediction result." (PMID 34395262, 2021). "Chromosome 7 harbors many interesting genes, including druggable targets such as the oncogenes EGFR, BRAF and MET, but at present their relation to the retention of chromosome 7 and the development of local recurrent disease in rectal cancer is unclear." (PMID 26048403, 2015). "The patient under observation in our study was also diagnosed with stage IV rectal cancer, along with low-MSI status (MSS) of the primary tumor and absence of mutations in the BRAF gene." (PMID 39518386, 2024). "Thus, we attempt to segment rectal cancer via 3D V-Net on T2WI and DWI and then compare the performance of radiomics in predicting the KRAS/NRAS/BRAF status between DL-based auto segmentation and manual-based segmentation." (PMID 34395262, 2021). "Of 57 rectal cancer patients in one study, 31.6% carried mutations in KRAS genes, and 9.6% had a loss of PTEN expression with no detected BRAF mutations." (PMID 24265711, 2013). "A similar pattern was detectable in rectal cancer, where PIK3CA and PTEN alterations were significantly overrepresented in the RAS/BRAF‐altered subgroup and EGFR, ERBB2, FGFR1, and FGFR3 alterations were significantly overrepresented in the RAS/BRAF‐wt subgroup." (PMID 39865537, 2025). "The aims of our study were to confirm that ctDNA analysis is feasible in a population of non-metastatic rectal cancer patients, to assess KRAS/BRAF mutations as markers for ctDNA detection, and to explore potential clinical implications of detectable KRAS mutations in ctDNA." (PMID 29362371, 2018). "However, in the present rectal cancer patient with wild-type KRAS and no MSI, we discovered a novel BRAF mutation that led to a triplet deletion of the coding nucleotides 1799–1801 (TGA1799–1801 deletion; VK600–601E)." (PMID 25636897, 2015).
rectal cancer (continued). "BRAF V600E mutant mCRC originating from the left‐side colon seemed to have superior overall survival compared with right‐side and rectal tumors, although statistical significance was not reached (median OS for left‐side, right‐side and rectal cancer: 20.4 m, 16.9 m, and 16.4 m, p = 0.296)." (PMID 36912150, 2023). "MSI rectal cancer displays other distinctive features, with a significant mucinous component and a decreased occurrence of MLH1 promoter hypermethylation and expression of BRAF mutations unlike Lynch dMMR colon cancer, which has no hMLH1promoter hypermethylation." (PMID 32923389, 2020). "Downstream events from KRAS, such as activation of BRAF, AKT and ERK, may also confer prognostic information but have not been tested in rectal cancer (RC)." (PMID 21910869, 2011). "Dewdney analyzed 165 patients with locally advanced rectal cancer and concluded that the addition of cetuximab did not improve CR or PFS rates; however, RR and OS rates (both secondary endpoints) were significantly improved in patients with wild-type KRAS/BRAF." (PMID 29282026, 2017).
squamous cell carcinoma (68 papers, 2009 to 2026). A carcinoma arising from squamous epithelial cells. "The BRAF p.V600E mutation is significantly associated with ATC exhibiting a squamous cell carcinoma phenotype and/or co-existing PTC." (PMID 40111709, 2025). "Initially suspected to be an aggressive squamous cell carcinoma, the diagnosis was confirmed as invasive cutaneous MM with a BRAF(V600) mutation via biopsy." (PMID 39767221, 2024). "It has be reported that the development of cutaneous squamous cell carcinomas during BRAF inhibitor therapy is caused by activation of the MAPK pathway in keratinocytes with preexisting RAS mutations commonly found in chronically sun damaged skin." (PMID 39776585, 2024). "Preclinical studies have shown that celecoxib and trametinib association increase dabrafenib efficacy and reduce BRAF-inhibitor-induced keratoacanthoma and squamous cell carcinoma by PLX7420." (PMID 33922284, 2021). "Similar to other studies, BRAF V600E mutation is more prevalent in adenocarcinoma type (80%) with exceptionally one case (20%) of squamous cell carcinoma." (PMID 31781475, 2019). "The p.Val639Ile mutation in BRAF has been annotated in COSMIC as associated with squamous-cell carcinoma in the lung." (PMID 29515789, 2018). "The most common side effect of trametinib (MEK inhibitor) in human patients is skin rush, and common toxicity associated with vemurafenib (BRAF inhibitor) is cutaneous abnormalities such as keratoacanthoma and squamous cell carcinoma by the mechanism of paradoxical MAPK pathway activation." (PMID 32792500, 2020). "However, the few studies published on BRAF mutations in squamous cell carcinomas would seem to indicate a low mutation rate." (PMID 24642661, 2014). "Following tumor invasion into the latissimus dorsi muscle, a biopsy of this metastatic lesion revealed a BRAF V600E-mutant squamous cell carcinoma (SCC) phenotype indicating a high-grade dedifferentiation from the primary PTC." (PMID 42136667, 2026). "Around 60% of instances of pure squamous cell carcinoma, which meets the 2017 WHO diagnostic criteria of squamous cell carcinoma, carry BRAF-V600E mutations, and their prognosis is the same as that of anaplastic carcinoma in general." (PMID 38737660, 2024). "In the AUS-nuclear group, a positive rFNA outcome (category V or VI) was observed in 54.8% of cancers (17 out of 31); among them, there were 16 PTCs (including 15 BRAF-positive ones) and one squamous cell carcinoma." (PMID 37686562, 2023). "In the case of adenocarcinoma (even in dimorphic combination with squamous cell carcinoma), a molecular genetic assay of EGFR mutations (18–21 exons), BRAF, V600E, ALK, and ROS1 is recommended." (PMID 35982978, 2022). "In terms of pathological features, BRAF-mutated NSCLC mostly comprises adenocarcinoma, and other histological types, including squamous cell carcinoma, have also been detected." (PMID 35814395, 2022). "This strategy also prevents paradoxical MAPK upregulation in BRAF wild type cells, thus avoiding the cutaneous squamous cell cancers that are promoted by mutant specific BRAF inhibitors." (PMID 33216832, 2020). "They recommend systematic biomarker/molecular testing including PDL1, EGFR, ALK, ROS1, and BRAF for all non-squamous cell carcinomas." (PMID 33704175, 2020). "Overall, the results in this study provide strong support for the development of KWM-EO into chemopreventive agents for squamous cell carcinoma patients or cancer patients taking BRAF inhibitor therapy." (PMID 31242703, 2019). "Regarding the histology of NSCLC with mutant BRAF gene, 4 cases (80%) were adenocarcinoma, while only one case (20%) was squamous cell carcinoma." (PMID 31781475, 2019).
squamous cell carcinoma (continued). "About 15% to 30% of patients treated with type I BRAF inhibitors, such as vemurafenib, develop squamous-cell carcinomas and keratoacanthomas." (PMID 22846499, 2012). "Intriguingly, 10%–15% of patients treated with BRAF-selective drugs develop squamous cell carcinoma (SCC)." (PMID 20141835, 2010). "ROS1 fusions were detected in 2.6% of non-squamous and 1.9% of squamous carcinomas, while BRAF V600E mutations were found in 3.7% and 1.9%, respectively." (PMID 41465119, 2025). "Long-term, the use of BRAF V600E inhibitors can lead to squamous cell carcinoma and keratoacanthoma, which may be attributed to paradoxical activation of MAP kinase in cells lacking the BRAF mutation." (PMID 35480100, 2022). "However, for the use of BRAF inhibitor monotherapy still raises the concern for development of serious side effects, particularly cutaneous side effects such as rash and squamous cell carcinoma." (PMID 30728904, 2019). "Increased GLUT-1 expression could also be detected in BRAF wild-type skin lesions, such as squamous cell carcinomas (SCC) and AK indicating that increased glucose metabolism contributes to tumor development of cutaneous neoplasia." (PMID 31334125, 2019). "A further reason to combine BRAF and MEK inhibitors in patients is to decrease the development of secondary RAS-driven cancers, such as squamous cell carcinomas and chronic lymphoblastic leukemia, that have been reported in patients inhibitor treated with BRAF monotherapy." (PMID 27713119, 2016). "None of the squamous cell carcinomas (0%: 0 out of 32) had detectable oncogenic mutations in either KRAS or BRAF." (PMID 21730982, 2011). "Unfortunately, while some of the anti-BRAF agents have shown promising anti-tumor activity in their clinical trials, many have been reported to have concerning toxic side effects, including the development of squamous cell carcinomas and basal cell carcinomas among others." (PMID 30975211, 2019). "Cutaneous toxicities, most notably squamous cell carcinomas (SCC), are considered a mechanism-related class effect of BRAF inhibitors." (PMID 39776585, 2024). "In the presence of BRAF inhibitors and activated RAS, BRAF forms a heterodimer with CRAF, which triggers the activation of the MEK/ERK pathway at the origin of pathologies such as squamous cell carcinoma." (PMID 34063682, 2021). "BRAF CNGs (13%) were more common in adenocarcinoma subtype and PIK3CA CNGs (36.4%) were more frequent in squamous cell carcinoma as compared to the other subtypes." (PMID 19238210, 2009). "In stage IV, molecular profiling (gene testing for EGFR, ALK, ROS1 and BRAF) was performed in 94.3% of patients with adenocarcinoma, non-specific carcinoma, or nonsmoking squamous cell carcinoma." (PMID 39147937, 2025). "As for pathologic feature, a majority of BRAF-mutated NSCLC were adenocarcinomas, other histologic type such as squamous cell carcinoma and NSCLC, not otherwise specified (NOS) were also detected." (PMID 32411601, 2020). "The same dosing regimen of topical BRAF inhibitor does not increase the incidence of cutaneous squamous cell carcinomas in mice." (PMID 27476449, 2016). "However, as reported for other BRAF inhibitors, dabrafenib also induced MAPK pathway activation in wild-type BRAF cells through CRAF (RAF1) signalling, potentially explaining the squamous cell carcinomas and keratoacanthomas arising in patients treated with BRAF inhibitors." (PMID 23844038, 2013).